LTBR (lymphotoxin beta receptor)
Diseases named in the same sentence as LTBR in open-access papers (continued):
Sharing a sentence is not in itself a finding about the gene and the disease.
colitis (7 papers, 2016 to 2025). Inflammation of the colon. "Our data indicate that neutrophil-specific loss of LTβR (LTβRΔN) is sufficient to exacerbate DSS colitis." (PMID 33568785, 2021). "Similar to LIGHT deficient mice, genetic ablation of LTβR resulted in exacerbated colitis with a similar overall phenotype, consistent with previous reports." (PMID 30524422, 2018). "The fundamental conundrum is that mice deficient for LTβR expression have a different phenotype in DSS colitis from mice deficient for both of its known ligands, LIGHT and LTβ." (PMID 30524422, 2018). "Thus, to determine whether LTαβ contributes to LTβR protective effects in in DSS-induced colitis, LTβ deficient mice were treated with DSS." (PMID 30524422, 2018). "Therefore, to more definitively address whether LTβR contributes to LIGHT mediated protection from DSS-induced colitis, we administered DSS in drinking water to LTβR deficient mice and controls." (PMID 30524422, 2018). "Together, these data suggest that LTβR expression by neutrophils is most important for protection of exacerbated DSS-induced colitis." (PMID 33568785, 2021). "Our results demonstrate that LIGHT signals to LTβR on neutrophils to suppress metabolic activation and thereby prevents exacerbated immune pathogenesis during colitis." (PMID 33568785, 2021). "Here, we aimed to determine the cell type(s) requiring LTβR and the mechanism critical for exacerbation of colitis." (PMID 33568785, 2021). "The results from these experiments suggest that LTβR is the critical receptor in maintaining the protective effect of LIGHT during DSS-induced colitis." (PMID 30524422, 2018). "Here, we report the generation and analysis of a variety of double-mutant mice to delineate the complex interplay of LIGHT/LTαβ with LTβR/HVEM signaling during DSS-induced colitis." (PMID 30524422, 2018). "We demonstrate that LIGHT signaling through LTβR is indispensable for protection from exacerbated DSS-induced colitis." (PMID 30524422, 2018). "In sum, the LIGHT/LTβR signaling critically contributes to DSS-induced colitis, but is subject to a degree of opposing regulation in the absence of LTαβ." (PMID 30524422, 2018). "The work of Macho-Fernandez indicated that LTβR signalling in intestinal epithelial cells promotes epithelial IL-23 production in a model of DSS-induced colitis." (PMID 27578924, 2016). "Signalling in macrophages is also protective; LTβR activation on macrophages has been shown to ameliorate acute colitis by inducing the expression of TRIM30α, a negative regulator that inhibits NF-κB activation and subsequent pro-inflammatory cytokine production." (PMID 41030453, 2025). "Validates LIGHT/HVEM as a therapeutic target in colitis: LTβR-Ig therapy ameliorated TNBS colitis." (PMID 41030453, 2025). "The energetically dysregulated phenotype and heightened ROS from LTβR-deficient neutrophils, resulting in more severe inflammation, could result in a feed-forward loop that exacerbates the DSS-induced colitis." (PMID 33568785, 2021). "Thus, our data identify a novel function for LTβR in neutrophils, limiting mitochondrial metabolism and ROS, that contributes to preventing severe colitis." (PMID 33568785, 2021). "To directly test the hypothesis that LTβ-LTβR signals drive severe colitis, we crossed two strains to generate double knock out (DKO) mice deficient for LTαβ and LTβR and determined if these mice exhibited augmented DSS-induced colitis progression." (PMID 30524422, 2018). "Given that other members of the TNF superfamily have been shown to play a role in a mouse model of colitis, we aimed to interrogate the LIGHT/LTαβ/LTβR/HVEM signaling network to determine if one or more of the involved components displays an important role in DSS-induced colitis pathogenesis." (PMID 30524422, 2018).
colitis (continued). "In sum, the LIGHT/LTαβ/LTβR signaling network contributes to DSS colitis, but there may be additional receptors or indirect effects, and therefore, the relationships between these receptors and ligands remains enigmatic." (PMID 30524422, 2018). "Thus, although the full mechanism remains elusive, our data strongly suggest that signaling of LTβR via LIGHT is necessary for protection from exacerbated DSS-induced colitis." (PMID 30524422, 2018). "Conversely, antibody mediated blockade of LTβR results in worsened colitis." (PMID 30524422, 2018). "Immunohistochemical and histological studies in both human IBD and experimental colitis models have demonstrated that tissue localization and abundance of LIGHT, HVEM, and LTβR are dynamically altered during intestinal inflammation." (PMID 41030453, 2025). "LTβR signalling in macrophages also induces the NF−κB inhibitor TRIM30α, which dampens acute DSS−induced colitis." (PMID 41030453, 2025). "In this study, we aimed to determine which LTβR expressing cell types were critical for providing protection from severe colitis, and which mechanism(s) downstream of the LIGHT–LTβR interaction were affording this protection." (PMID 33568785, 2021). "We found that LTβR mRNA is expressed by fibroblasts, neutrophils and other CD11b+ cells at steady-state and during DSS-induced colitis." (PMID 30524422, 2018). "Mice lacking LTβR in neutrophils developed more severe DSS colitis with massive neutrophil accumulation." (PMID 41030453, 2025). "Together, these data suggest that metabolic dysregulation, including enhanced oxidative and glycolytic metabolism and ROS production in mice with neutrophil-specific LTβR deletion, persisted in the colon during DSS colitis and contributed to exacerbated disease." (PMID 33568785, 2021). "In addition, deletion of lymphotoxin beta receptor (LTβR), which binds LIGHT, also led to aggravated colitis pathogenesis." (PMID 33568785, 2021). "Specific deletion of LTβR in neutrophils (LTβRΔN), but not in several other cell types, was sufficient to induce aggravated colitis and colonic neutrophil accumulation." (PMID 33568785, 2021). "Together, these results demonstrate that LTβR activation is necessary for protection from exacerbated DSS-induced colitis, with a phenotype similar to the absence of LIGHT." (PMID 30524422, 2018). "Here we demonstrate that LIGHT signaling through LTβR, rather than HVEM, plays a critical role in the progression of DSS-induced colitis, as LTβR deficient mice exhibit a more severe disease phenotype." (PMID 30524422, 2018). "While LTαβ signaling by itself is not critical for altering the severity of colitis, LTαβ deletion rescued the pathogenic effect of LIGHT deletion, but not of LTβR deletion." (PMID 30524422, 2018). "In addition, interaction of surface LT on ILC3s with LTβR on intestinal epithelial cells can lead to IL-22 production in colon in C. rodentium and DSS-induced colitis models." (PMID 27578924, 2016). "A recent animal experiment in a mouse model of colitis found that the binding of LIGHT and LTβR limited glycolysis, respiration, and reactive oxygen species production in the mitochondria of neutrophils, and the inhibition of LTβR expression reversed severe colitis." (PMID 37108160, 2023). "LTβR-dependent effects of LTβ in moderating severe colitis due to expression by T cells are not ruled out by our work, however, and overall the data indicate how the analysis of cell-type-specific effects of gene deficiency are essential in this complex system of ligands and receptors." (PMID 33568785, 2021). "Additionally, HVEM activation does not seem to contribute to DSS-induced colitis, even in the absence of LTβR." (PMID 30524422, 2018). "Notably, if HVEM signals drive severe inflammation in the absence of LTβR, mice deficient in both receptors should be protected from exacerbated DSS-induced colitis." (PMID 30524422, 2018).
colitis (continued). "LIGHT signaling through LTβR, rather than HVEM, attenuated dextran sodium sulfate–induced colitis, with Light−/− and Ltbr−/− mice exhibiting a more severe pathology." (PMID 35604387, 2022).
glioblastoma (7 papers, 2018 to 2023). The most malignant astrocytic tumor (WHO grade IV). "Next, we utilized a spatial transcriptomics dataset of human glioblastomas to map LTB and LTBR expression in situ." (PMID 36230839, 2022). "The addition of agonistic LTβR antibodies to anti-VEGF plus anti-PDL1 therapy, thus fully activating the LTβR signaling cues, further increased HEV numbers and maturation in breast and pancreatic cancer and sensitized glioblastoma to the therapy." (PMID 34484246, 2021). "LTβR agonistic antibodies (anti-LTβR) were also reported to induce MECA-79+ TA-HEV and to enhance lymphocyte infiltration in distinct mouse tumor models, and treatment with anti-LTβR enabled response to anti-VEGFR2 and anti-PD-L1 combination therapy in a recalcitrant glioblastoma model." (PMID 33956259, 2021). "Indeed, in glioblastoma (GBM), administration of LTβR agonist alone had no impact on the tumour growth and burden." (PMID 37287625, 2023).
hepatocellular carcinoma (7 papers, 2012 to 2026). A malignant tumor that arises from hepatocytes. "Silencing of TRAF5 enhances necroptosis in hepatocellular carcinoma by inhibiting LTBR-mediated NF-κB signaling [Data set]." (PMID 37366426, 2023). "Lymphotoxin β receptor (LTBR), a member of the tumor necrosis factor (TNF)/TNF receptor superfamily, significantly affects the activation and clonal expansion of CD8+ T cells and has been found to be associated with the development and progression of hepatocellular carcinoma." (PMID 34109216, 2021). "In patients with non-alcoholic steatohepatitis (NASH)-derived hepatocellular carcinoma (HCC), renal cell carcinoma (RCC) and head and neck squamous cell carcinoma (HNSCC), increased expression of LTβR correlated with disease progression and a worsened prognosis." (PMID 39215104, 2024).
rheumatoid arthritis (7 papers, 2009 to 2024). A chronic, systemic autoimmune disorder characterized by inflammation in the synovial membranes and articular surfaces. "According to recent studies, LTβR has been implicated in a proinflammatory role in various inflammatory illnesses, including rheumatoid arthritis, autoimmune hepatitis, and pancreatitis." (PMID 39707217, 2024). "It is also consistent with one study that showed that LTαβ, which only binds LTβR, induced mRNA or protein expression of ICAM-1, and several chemokines including CCL5, in rheumatoid arthritis-derived fibroblast-like synoviocytes." (PMID 29616048, 2018). "In rheumatoid arthritis, sustained activation of LTβR triggers non-canonical NF-κB signaling, promoting the expression of inflammatory mediators and adhesion molecules in vascular endothelial cells." (PMID 39707217, 2024).
diabetes (6 papers, 2007 to 2024). "In addition, soluble LTβR-Ig transgene expression on the NOD background blocked diabetes development." (PMID 19222863, 2009). "In non-obese diabetic (NOD) mice, treatment with LTβR-Ig prevented insulin-dependent diabetes mellitus (IDDM) and reversed insulitis." (PMID 19222863, 2009).
colorectal cancer (5 papers, 2012 to 2025). A primary or metastatic malignant neoplasm that affects the colon or rectum. "Overexpression of LTBR has been reported in some cancers, such as colorectal cancer and neck squamous cell carcinomas, and LTBR has been a potential therapeutic target for cancer." (PMID 37366426, 2023). "Moreover, LTBR has been indicated to trigger the proliferation of colorectal cancer cells." (PMID 37366426, 2023). "Here, we targeted NIK in ECs, as these are the cells expressing NIK in relevant patient tissues, and subsequently we found that NIK expression is critical for LTβR-induced angiogenesis associated with colorectal cancer, whereas it does not seem to affect GF-induced sprouting." (PMID 29983872, 2018). "Sub-lethal tumor cell irradiation alone exhibited minimal cell death, but effectively sensitized three of three colorectal carcinoma cells to both TRAIL and Fas-induced apoptosis, but not LTβR-induced death." (PMID 22389673, 2012).
leukemia (5 papers, 2016 to 2023). A malignant (clonal) hematologic disorder, involving hematopoietic stem cells and characterized by the presence of primitive or atypical myeloid or lymphoid cells in the bone marrow and the blood. "Here, the authors show that LIGHT and its receptor LTβR promote quiescence and self-renewal of HSCs and that LTβR deficiency promotes survival in a mouse leukaemia model." (PMID 33594067, 2021). "Combined, these studies suggest a pathogenic role for the LTβR pathway in leukemia progression." (PMID 36912771, 2023). "FACS analysis revealed that LTβR was expressed on LSCs and leukemia progenitors with the highest expression on LT-LSCs." (PMID 33594067, 2021). "LTβR signaling may also modulate the leukemic microenvironment: inactivation of LTβR results in a significant delay in leukemia onset in TEL-JAK2 mice, which spontaneously develop T-cell leukemia, presumably due to the loss of LTβR signaling in thymic stromal cells." (PMID 33917839, 2021). "Genetic or pharmacological blockade of LTβR signaling in MSCs restores lymphopoiesis but not erythropoiesis at the onset of leukemia, which in turn reduces leukemic cell growth and extends survival of transplant recipients." (PMID 36912771, 2023).
lymphoma (5 papers, 2013 to 2024). A malignant (clonal) proliferation of B- lymphocytes or T- lymphocytes which involves the lymph nodes, bone marrow and/or extranodal sites. "We therefore asked if expanding lymphoma B cells act competitively to LTα1β2high-expressing normal B cells and, thus, cause insufficient LTβR stimulation in FRCs." (PMID 34706240, 2021). "Interference with the VEGF receptor-3 and the LTBR signaling pathways in high-grade b-cell lymphoma inhibited lymphoma angiogenesis." (PMID 38175686, 2024). "In lymphoma-challenged LNs, antibody-mediated LTβR stimulation was sufficient to restore HECs and their functional surface molecule repertoire." (PMID 34706240, 2021). "An effort to restore CCL21 expression in FRCs, as mediated by LTβR antibody stimulation or overexpression of LTβR ligands in lymphoma cells, was unsuccessful, indicating that FRCs require mechanosensitive signaling to gain a mature myofibroblastic state." (PMID 34706240, 2021). "Inhibition of LTβR signaling by anti- LTβR antibody or knockdown of LTα impaired cell interaction between lymphoma cell and stromal cell, potentially by disrupting production of CCL19 and CCL21 by stromal cells which are ligands for CCR7." (PMID 25211095, 2014). "Conditional knockout of the LTβR in ECs (Cdh5CreERT2xLtbrfl/fl referred to as Ltbrfl/fl) caused a reduction of PNAd, CCL21, and ICAM1 expression in BECs, similar to the dedifferentiation observed in HECs during lymphoma challenge." (PMID 34706240, 2021). "The expression of the LTβR in BECs and its ligands Ltα, Ltβ, and Tnfsf14 (LIGHT) in DCs remained unchanged in lymphoma." (PMID 34706240, 2021). "Next, we silenced LTβR expression in FACS-purified BM CD34+ HSPCs from untreated staging negative lymphoma patients (control samples) using small interfering RNA (siRNA)." (PMID 33594067, 2021). "In contrast to infection models, lymphoma did not allow a recovery of HEVs, FRC-derived CCL21 expression, or the conduit network, although lymphoma B cells potentially can activate LTβR signaling." (PMID 34706240, 2021). "Specifically, for down-regulated genes: LTBR is a receptor for LTbeta in the NF-κB alternative pathway in humans and CD40LG (or CD40L) can be a ligand for NF-κB alternative pathway, both indicating canonical pathway activation in lymphoma rather than alternative pathway activation for NF-κB." (PMID 24023754, 2013).
ovarian carcinoma (5 papers, 2018 to 2024). A malignant neoplasm originating from the surface ovarian epithelium. "Studies on ovarian cancer cells demonstrated that TNF-β overexpression is commonly found in different ovarian cancer subtypes, and that the LTBR is expressed ubiquitously in ovarian cancer cells as well as cancer-associated fibroblasts." (PMID 30002278, 2018). "The therapeutic potential of targeting the lymphotoxin-LTBR and CXCL11-CXCR3 signaling pathways has been demonstrated in ovarian cancer." (PMID 38175686, 2024). "Additionally, lymphotoxin derived from cancer cells can induce chemokine expression in stromal fibroblasts via the LTBR-NF-κB signaling pathway, while the lymphotoxin-LTBR and CXCL11-CXCR3 signaling pathways serve as therapeutic targets in ovarian cancer." (PMID 38175686, 2024). "Eight immune factors (IFT57, MAL, ANXA4, SCRN1, LTBR, KIFAP3, HSPA5, and LTN1) were positively correlated with poor prognosis of ovarian cancer, whereas six immune factors (PSMB9, FOXJ1, CTSH, MIF, CTSD, and PSMB8) were negatively correlated with poor prognosis of ovarian cancer." (PMID 34109184, 2021).
viral infection (5 papers, 2015 to 2022). "In the lymph node, LTB–LTBR signaling between B cells and macrophages maintains macrophage responsivity to viral infections, and microglial LTBR has roles in de- and remyelination." (PMID 36333772, 2022). "LTβR signaling has been reported to be crucially involved in many cellular processes and molecular events, and we are particularly interested in its role in bacterial and viral infection." (PMID 30469426, 2018). "Therefore, we used IPEC-J2 cells, a non-transformed, non-tumorigenic porcine cell line derived from jejunal intestinal regions, to investigate the effects of LTβR on cell proliferation, apoptosis and viral infection." (PMID 30469426, 2018). "Our data and others suggest that LTβR-Ig could be a candidate therapy for HSE to control viral infection and limit excessive inflammation within neuron tissue." (PMID 25993659, 2015). "In addition, the role of LTβR in viral infection was investigated." (PMID 30469426, 2018). "In contrast, targeting LTβR in CCL19-expressing cells (CCL19-Cre) did not affect LN development and structure, but impaired resistance to viral infection." (PMID 34335629, 2021).
Hepatitis (4 papers, 2012 to 2024). Inflammation of the liver. "Lymphotoxin-β receptor (LTβR) signalling is critically involved in hepatitis and liver tumorigenesis." (PMID 26206664, 2016). "This mouse model demonstrated that LTβR plays a pivotal role in hepatitis-induced HCC onset and progression, and that disruption of LTβR signaling pathway may have the potential for clinical investigation." (PMID 23233866, 2012). "It has been established that LTBR signaling pathway has an impact on hepatitis B virus (HBV) infection, hepatitis, and hepatocarcinogenesis." (PMID 38175686, 2024).